HGF (hepatocyte growth factor)
Diseases named in the same sentence as HGF in open-access papers (continued):
Sharing a sentence is not in itself a finding about the gene and the disease.
prostate carcinoma (continued). "FYN is downstream of the HGF/MET signaling loop, and HGF can effectively regulate FYN activity, which promotes prostate cancer biology by promoting cell growth and regulating targeted chemotaxis-translocation components in prostate cancer biology." (PMID 36740671, 2023). "While there has been little research focused on the modulating function of SIPA1 on the regulation of HGF/MET in TJs, previous work from the host laboratory indicated that in breast and prostate cancer cells, the presence of SIPA1 was required for the regulation of HGF/MET in TJs." (PMID 33917539, 2021). "Studies have shown that NK4 is used in the treatment of prostate cancer, The mechanism by which NK4 promotes apoptosis in DU145 cells maybe its inhibitory effect on HGF-induced proliferation, leading to increased apoptosis." (PMID 34970492, 2021). "In prostate cancer, PC-3 cells had reduced TER and increased PCP after treatment with HGF." (PMID 33917539, 2021). "The hepatocyte growth factor (HGF)/c-Met cell is activated by TMPRSS2, provoking the survival pathway of HGF/c-Met receptor tyrosine kinase signaling and stimulating a pro-invasive role in prostate cancer cells." (PMID 34068970, 2021). "HGF induces cell adhesion and migration in a c-Met-negative prostate cancer cell line on the basis of a low-affinity interaction between its heparin-binding domain and nucleolin." (PMID 28212658, 2017). "As the receptor for HGF, c-MET, has been shown to be upregulated in androgen-insensitive and metastatic prostate cancer cells, it would be interesting in future work to test whether this is linked to increased invasiveness via EphA receptor-mediated CIL." (PMID 24795148, 2014). "c-Met stable expression cell lines were constructed in c-Met- and HGF-negative LNCaP prostate cancer cells by cell transfection." (PMID 25202379, 2014). "Furthermore, we have published data from a Phase II clinical trial demonstrating that EGCG, in the form of Polyphenon E, is able to decrease serum levels of prostate serum antigen (PSA), HGF and VEGF in men with prostate cancer." (PMID 25272043, 2014). "Among these factors, EMT induction by the HGF/c-Met axis is essential in certain types of cancer, however, to the best of our knowledge, the role of c-Met in the progression of prostate cancer has not yet been reported." (PMID 25202379, 2014). "HGF did however induce scattering of human prostate cancer cell line PC3 (data not shown) at similar dose range used in previous reports." (PMID 24098477, 2013). "DU145 cells were used because these prostate cancer cells do not phosphorylate c-Met without exogenous HGF." (PMID 22639908, 2012). "Considering the lack of alternative HGF/c-MET models for prostate cancer, we specifically aimed at validating our results in human prostate cancer specimens." (PMID 22110593, 2011). "Further complicating Met/HGF correlations and prostate cancer models is the fact that high Met expression levels do not always invoke concentration-dependent responses to HGF treatment." (PMID 16869958, 2006). "Indeed, most studies on the HGF/MET-mediated phosphorylation of STMN1 have not used prostate cancer cell lines, nor have they investigated in detail the regulation of both tSTMN1 and STMN1 phosphorylation during cell cycle progression." (PMID 40723207, 2025). "However, HGF expression is reduced in prostate cancer, compared to in normal tissues, and is negatively correlated with hepsin in prostate cancer." (PMID 35204704, 2022). "Indeed, the level of hepatocyte growth factor (HGF) in the TME of metastatic prostate cancer is higher than that of non-metastatic cancers." (PMID 33535458, 2021). "In addition, HVS substantially impaired c-Met-mediated scattering phenotype of DU145 prostate cancer cells in a dose-responsive fashion, while similar treatment doses did not affect EGF-mediated cell scattering, confirming a direct inhibition of the HGF/c-Met signaling pathway." (PMID 27086914, 2016).
prostate carcinoma (continued). "Further studies revealed that niclosamide blocked acidic pHe, HGF, and epidermal growth factor (EGF)-induced anterograde lysosome redistribution, protease secretion, motility, and invasion of DU145 castrate resistant prostate cancer cells at clinically relevant concentrations." (PMID 26784896, 2016). "In a prior study we showed that prostate cancer PC-3 cells exhibit constitutively activated c-Met without exogenous hepatocyte growth factor (HGF); however whether this characteristic is due to an endogenous HGF/c-Met autocrine loop remains controversial." (PMID 22639908, 2012). "Working with the LNCaP prostate cancer progression model, we found that these cells could respond to HGF stimulation, even in the absence of Met, the only known HGF receptor." (PMID 16869958, 2006). "Interestingly, HVS did not affect the EGF-mediated scattering in prostate cancer cells, confirming that this oleocanthal-based derivative significantly impaired tumor cell motility and invasiveness mediated only by the HGF/c-Met axis and eliminated the possibility of off-target effects." (PMID 27086914, 2016). "The results demonstrated a significant reduction in PSA, HGF, and VEGF serum levels in males with prostate cancer after a short course of treatment with EGCG (PPE) with no increase in liver enzymes." (PMID 37446908, 2023).
colon carcinoma (98 papers, 1995 to 2026). "Metastasis-associated in colon cancer 1 was shown to play a differential role in breast and colorectal cancer via HGF/c-Met signaling." (PMID 33425885, 2020). "HGF has recently been shown to be constitutively produced in a relatively large subset (~30%) of primary colon tumors and in established colon cancer cell lines due to mutations in the HGF promoter region." (PMID 28420162, 2017). "HGF has recently been shown to be produced in a relatively large subset (~30%) of primary colon tumors and established colon cancer cell lines due to mutations in the HGF promoter region." (PMID 27121052, 2016). "In contrast, HGF has been recently shown to be produced in a relatively large subset (~30%) of primary colon tumors and established colon cancer cell lines due to mutations in the HGF promoter region." (PMID 27121052, 2016). "In fact, in colorectal cancer, HGF has been reported to elicit its effects through secretion by stromal cells such as fibroblasts and cancer-associated fibroblast, which then activates c-Met on adjacent colon cancer epithelial cells in a paracrine fashion." (PMID 34853656, 2021). "Indeed, high serum levels of HGF have recently been shown to be associated with resistance to EGFRi therapy in colon cancer patients with WT KRas." (PMID 27121052, 2016). "Our findings demonstrate that overproduction of HGF can underlie primary resistance to EGFRi in colon cancer cells that harbor WT KRas and suggest that these patients may benefit from combined therapy with inhibitors of EGFR and HGF." (PMID 27121052, 2016). "In 2010, Vermeulen and colleagues demonstrated that factors secreted by myofibroblasts, especially hepatocyte growth factor (HGF), amplify Wnt signaling in colon cancer cells." (PMID 38673727, 2024). "It was evident that TGFβ stimulates the CAFs in the colon, which secretes various factors, such as tenascin C and hepatocyte growth factor (HGF), to play influential roles in the invasion of colon cancer cells." (PMID 38361941, 2024). "One study had defined a tumor-associated fibroblast subpopulation with high F3 expression in colon cancer, which can secrete more HGF factors and promote tumor proliferation by activating various pathways such as RAS or PI3K." (PMID 39113997, 2024). "Myofibroblast-secreted HGF can activate β-catenin-dependent transcription and colon cancer stem cell clonogenicity." (PMID 38817451, 2024). "In line with this evidence, we have shown that HGF, which can be produced by tumor‐associated fibroblasts, induced entrectinib resistance in NTRK1 rearranged colon cancer and ROS1 rearranged NSCLC models." (PMID 36416133, 2023). "These genes encode the extracellular matrix proteins LAMA3 and LAMC2, which have been detected in invasive colon cancer cells and are regulated by transforming growth factor beta 1 and the hepatocyte growth factor produced in the tumor microenvironment." (PMID 36077674, 2022). "Rab31 was reported to promote the migration of colon cancer cell lines by paracrine HGF, and HGF inhibition abolished the migration of cancer cells mediated by Rab31 expression." (PMID 34975321, 2022). "It is not difficult to find a close relationship between MACC1 and c-MET as well as HGF in colon cancer by extracting data from StarBase Pan-cancer." (PMID 35874635, 2022). "MACC1 was first described in 2009 as a critical pro‐metastatic TF regulating HGF/c‐Met signaling axis in human colon carcinoma." (PMID 33751856, 2021). "MET and its ligand HGF have also been shown to interact with Wnt signaling to maintain stemness in colon cancer cells." (PMID 34069138, 2021).
colon carcinoma (continued). "In colon cancer,myofibroblasts in the tumour niche orchestrate high Wnt activity via β-cateninlocalization through hepatocyte growth factor secretion, which facilitates thereprogramming of the colon cancer cells to a stem cell-like progenitor state." (PMID 33465324, 2021). "In colon cancer, HGF secreted by fibroblasts has been shown to drive colon cancer cell proliferation through c-MET dependent signalling." (PMID 33271944, 2020). "In conclusion, we present RAB31 as an important regulator of HGF secretion in CRC-derived cancer-associated fibroblasts, which plays an important role in the progression of colon cancer through activating HGF/Met signaling in cancer cells." (PMID 33072555, 2020). "Lastly, activation of HGF/c-Met signaling also contributes to the cancer stem cell phenotype in other types of cancer such as: gliomas, colon cancer, head and neck cancer, prostate cancer and pancreatic cancer." (PMID 30214428, 2018). "It has been shown that TGF-β-stimulated colon CAFs are able to secrete scatter factor/hepatocyte growth factor (SF/HGF) and tenascin C, and thereby promote invasiveness of colon cancer cells." (PMID 30356678, 2018). "Recently, established colon cancer cell lines and primary colon tumors have been shown to produce large amounts of HGF." (PMID 30214428, 2018). "Consistent with preclinical studies, increased levels of HGF in colon cancer patients with WT KRAS, and in NSCLC patients correlate with lack of response to EGFR inhibitors." (PMID 28420162, 2017). "In our previous study, we demonstrated a role of the hepatocyte growth factor (HGF)/MET pathway in the regulation of colon cancer cell proliferation and cetuximab resistance." (PMID 28573382, 2017). "For example, HGF in colon cancer cells and TGF-β in mammary epithelial cells can induce the EMT-CSC program." (PMID 27901498, 2017). "We have previously shown the GC-sensitive and GR-regulated release of several pro-angiogenic factors (TNC, TGFβ and HGF/SF) by cultured colon cancer-derived myofibroblasts." (PMID 27717848, 2017). "Elevated levels of HGF are associated with poor survival of stage II and stage III colon cancer patients." (PMID 28420162, 2017). "HGF/MET signaling has been linked to resistance to EGFRI therapy in many types of cancer, like NSCLC (gefitinib) and colon cancer (cetuximab)." (PMID 28456787, 2017). "By performing subcellular fractionation, we further demonstrated that Chk1 phosphorylation mainly occurred in the nucleus in colon cancer cells, and HGF activated Chk1 in both the cytoplasm and the nucleus." (PMID 28573382, 2017). "Through the secretion of hepatocyte growth factor (HGF), CAFs from colon cancer were demonstrated to support CSC properties through the induction of Wnt/β-catenin signaling." (PMID 28337221, 2017). "In the present study, we demonstrated that HGF moderately activated Chk1 phosphorylation in colon cancer cells by upregulating TopBP1 and RAD51, and promoting TopBP1–ATR complex formation." (PMID 28573382, 2017). "Colon cancer patients, particularly patients with lymph node and liver metastasis, have increased levels of HGF in serum and in tumor tissues." (PMID 28420162, 2017). "We confirmed that HGF is sufficient to promote the growth and survival of colon cancer cells and that antibody-mediated neutralization of HGF abrogates the tumor-promoting activity of fibroblasts." (PMID 27121052, 2016). "Our findings show that overproduction of HGF can cause primary resistance to EGFRi in colon cancer cells and suggest that such patients would benefit from combined therapy with inhibitors of EGFR and HGF." (PMID 27121052, 2016). "SRI 31215 overcomes primary resistance to cetuximab and gefitinib in HGF-producing colon cancer cells and prevents fibroblast-mediated resistance to EGFR inhibitors." (PMID 27121052, 2016). "We now report that colon carcinoma HT29 cells (express c-Met) can also be used to monitor HGF-induced cell scattering." (PMID 24352566, 2014).
colon carcinoma (continued). "In colon carcinoma, myofibroblasts express hepatocyte growth factor (HGF), a ligand of c-Met receptor tyrosine kinase, leading to co-stimulation and enhancement of Wnt signaling in differentiated cancer cells and promoting their stem/progenitor properties." (PMID 22405133, 2012). "In colon cancer, myofibroblast-secreted HGF restored a stem-like phenotype in more differentiated cells in vitro and in vivo." (PMID 22110593, 2011). "Recently, MACC1 has been identified as a prognosis biomarker for colon cancer, which promotes proliferation, invasion and hepatocyte growth factor (HGF)-induced scattering of colon cancer cells in vitro and in vivo." (PMID 21923915, 2011). "The mRNA expression of VEGF isoforms, PDGF, HGF and their receptors were determined in three colon cancer cell lines (HCT116, HT29 and Caco-2) by RT-PCR." (PMID 20950431, 2010). "In this regard, c-Src co-operates with migratory growth factors, including epidermal growth factor (EGF), both to induce epithelial cell migration, as well as to induce hepatocyte growth factor (HGF)- or EGF-induced invasion of colon cancer cells in vitro." (PMID 12402152, 2002). "A previous study reported that TNC and HGF could together provide a convergent pro-invasive signal in human colon cancer cells by inactivating RhoA and activating Rac, respectively." (PMID 36765641, 2023). "We next explored whether the HGF secretion induced by CCL20 stimulation of colon cancer epithelial cells is relevant to the functional effects of CCL20." (PMID 34853656, 2021). "We demonstrate that increased RAB31 expression in CAFs, a major component of stromal cells, may promote colon cancer progression by increasing HGF secretion which subsequently activates HGF/Met signaling in CRC cells." (PMID 33072555, 2020). "The combined results of cytokine array and transwell assay suggest that HGF may be a key factor in CAF-mediated migration of colon cancer cells." (PMID 33072555, 2020). "Metastasis-associated in colon cancer 1 (MACC1) was first identified in colon tumors by differential display RT-PCR, and was shown to be involved in the regulation of colon tumor growth and metastasis through the hepatocyte growth factor (HGF)/c-Met signaling pathway." (PMID 33425885, 2020). "Besides that, mechanistically, myofibroblasts isolated from colon cancer tissue were shown to promote tumor cell invasion via mechanism that involves tenascin-C, scatter factor/HGF, RhoA and Rac." (PMID 30242440, 2019). "In addition, tumor microenvironment-derived HGF augmented Wnt/β-catenin signaling and clonogenicity in colon cancer stem cells characterized by high Wnt reporter activity." (PMID 31212972, 2019). "Moreover, HGF induces Wnt signaling in colon cancer cells, resulting in a cancer stem cell phenotype in vitro and in vivo." (PMID 30214428, 2018). "Indeed, myofibroblast-derived HGF has been shown to induce Wnt signaling in colon cancer cells and to confer the cancer stem cell phenotype in vitro and in vivo." (PMID 28420162, 2017). "In this study, we explored the role of HGF on the ATR/Chk1 pathway in colon cancer cells." (PMID 28573382, 2017). "Inhibition of the MET kinase activity by JNJ38877605 or inhibition of the biological activity of HGF by SRI31215, a novel small molecule inhibitor of pro-HGF activation, restored sensitivity of HGF-producing colon cancer cells to EGFR inhibition by blocking autocrine MET activation." (PMID 28420162, 2017). "HGF-producing colon cancer cells display autocrine activation of MET signaling." (PMID 28420162, 2017). "In this study, we demonstrated a novel role of HGF in the activation of Chk1 phosphorylation in colon cancer cells, regardless of RAS mutation status." (PMID 28573382, 2017).